RNU6-1229P (RNA, U6 small nuclear 1229, pseudogene)
Gene: Small nuclear RNA gene on chromosome 7 (65,023,204 to 65,023,310, reverse strand). Ensembl gene ENSG00000201165.
Homologues: Orthologues: chimpanzee U6 (97% identical), macaque U6 (93% identical). Paralogues in human: RNU6-973P (97% identical), RNU6-1126P (91% identical), RNU6-26P (87% identical), RNU6-1024P (86% identical), RNU6-1060P (86% identical), RNU6-15P (86% identical), RNU6-166P (86% identical), RNU6-19P (86% identical), RNU6-266P (86% identical), RNU6-41P (86% identical), RNU6-71P (86% identical), RNU6-949P (86% identical), and 1289 more.